VSIG10 (V-set and immunoglobulin domain containing 10)
Tractability: Antibody: UniProt predicts a signal peptide or a membrane-spanning region; its Gene Ontology location is reachable by antibodies, with medium confidence. PROTAC: ubiquitination databases record sites on it.
Gene: Protein-coding gene on chromosome 12 (118,063,593 to 118,136,026, reverse strand). Ensembl gene ENSG00000176834.
Subcellular location: Membrane
Subcellular location (Human Protein Atlas): Cytosol; Centriolar satellite
Gene Ontology:
Molecular function: cell adhesion molecule binding
Biological process: cell-cell adhesion; synapse assembly
Cellular component: cell-cell junction; plasma membrane; membrane
Genetic constraint (gnomAD): Loss-of-function variants: 49 observed, 60.93 expected, observed/expected ratio (o/e) 0.8, 90% interval 0.64 to 1.02. The upper end of that interval is the gene's LOEUF score, 1.02, which puts it in group 4 of 6, group 1 being the genes least tolerant of losing a copy. Missense variants: 628 observed, 685.13 expected, observed/expected ratio (o/e) 0.92, 90% interval 0.86 to 0.98. Synonymous variants: 259 observed, 270.32 expected, observed/expected ratio (o/e) 0.96, 90% interval 0.87 to 1.06.
Homologues: Orthologues: chimpanzee VSIG10 (97% identical), macaque VSIG10 (94% identical), rabbit VSIG10 (76% identical), pig VSIG10 (76% identical), guinea pig VSIG10 (75% identical), rat Vsig10 (70% identical), mouse Vsig10 (67% identical), tropical clawed frog vsig10 (35% identical). Paralogues in human: IGSF10 (20% identical), IGSF9 (18% identical), NRCAM (18% identical), ROBO1 (18% identical), ROBO2 (18% identical), CNTN3 (18% identical), CNTN4 (18% identical), CNTN6 (18% identical), NFASC (18% identical), CNTN2 (18% identical), NCAM2 (18% identical), PRTG (18% identical), and 24 more.
Diseases named in the same sentence as VSIG10 in open-access papers:
VSIG10 is named in the same sentence as 3 diseases in open-access papers, as found by Europe PMC text mining. Sharing a sentence is not in itself a finding about the gene and the disease. The quoted sentences say what the papers report.
colon cancer (2 papers, 2022). "Finally, VSIG10 codes for an immunoglobulin-related protein associated with both cell adhesion and macrophage involvement in colonic pathologies including colon cancer." (PMID 36139690, 2022). "Furthermore, the roles of VSIG10 and DNAJC28, which may be involved in stem cell function, in IBD and colon cancer, remain unknown." (PMID 35323693, 2022).
cancer (1 paper, 2022). A tumor composed of atypical neoplastic, often pleomorphic cells that invade other tissues. "VSIG10 was highly expressed on both normal and cancer epithelial cells based on transcriptional data." (PMID 36189222, 2022). "Hence, the generation of anti-VSIG10 antibodies, as reported in the patent, may present a promising DC-targeting ICB cancer immunotherapy." (PMID 36189222, 2022).
VSIG10 also shares sentences with these, for which no sentence is quoted: COVID-19 (1 paper).